APOC3 (apolipoprotein C3)
Diseases named in the same sentence as APOC3 in open-access papers (continued):
Sharing a sentence is not in itself a finding about the gene and the disease.
atherosclerosis (continued). "The reduction in atherosclerosis in diabetes with decreasing APOC3 levels was also observed in the setting of GalNAc-modified APOC3 ASO treatment." (PMID 38743496, 2024). "APOC3 presumably enters a lesion of atherosclerosis bound to APOB-containing lipoproteins (small VLDLs, RLPs or LDL) or bound to HDL." (PMID 37972731, 2024). "Further investigation on the effects and benefits of APOC3 inhibition in different animal models of atherosclerosis need to be carried out." (PMID 37762360, 2023). "Our experimental evidence provides new insight into the possibility that ApoC3 will be a potential therapeutic target for the treatment of FH and atherosclerosis." (PMID 35187136, 2022). "To determine if apoC-III–knockdown strategies can improve atherosclerosis, we administered an ASO against Apoc3 (50 mg/kg/w) to mouse models that differ in their metabolic response to apoC-III inhibition." (PMID 35653195, 2022). "CRISPR/Cas9 has been used to make an Apoc3 knockout (KO) hamster model which showed reduced triglycerides and protection from atherosclerosis [53•], supporting APOC3 as a promising target." (PMID 35230602, 2022). "A previous study reported that ApoC3 delays the catabolism of triglyceride-rich particles, which is crucial for the advancement of atherosclerosis." (PMID 35453604, 2022). "Apolipoprotein C3 (ApoC3) delays the catabolism of triglyceride-rich particles and plays a critical role in atherosclerosis progression." (PMID 35453604, 2022). "Our unexpected findings provide new insight into the possibility that targeting ApoC3 will be a potential therapeutic approach for the treatment of FH with severe refractory hypercholesterolemia and atherosclerosis." (PMID 35187136, 2022). "Since patients with CV risk factors are more susceptible to develop atherosclerosis, SLE patients with elevated ApoC3 can represent a subset of patients at increased risk for CV disease." (PMID 35538496, 2022). "We aim to create APOC3-knockout (KO) rabbits and explore the effects of APOC3 deletion on the occurrence and development of atherosclerosis." (PMID 34922545, 2021). "These images of atherosclerotic lesions from the T1D mouse model of accelerated atherosclerosis show that APOC3 immunoreactivity is present in the artery wall and substantially colocalizes with apolipoprotein B (APOB)." (PMID 33554869, 2021). "Based on genetically modified mouse models, such as LPL−/−, GPIHBP1−/−, and ApoC3 transgenic mice, triglycerides were demonstrated to promote atherosclerosis." (PMID 34796210, 2021). "This study offered ApoC3 as a promising gene therapy target for hyperlipidemia-induced atherosclerosis." (PMID 34805315, 2021). "As another promising target for atherosclerosis, ApoC3 is predominantly expressed in liver and to a smaller extent in the intestine." (PMID 34805315, 2021). "Suppressing APOC3 expression with anti-sense oligonucleotides (ASO) lowered both plasma apoC-III levels and atherosclerosis." (PMID 32849270, 2020). "Together, there is strong evidence to suggest that APOC3 overexpression promotes atherosclerosis in mouse models." (PMID 32849290, 2020). "Plasma levels of proprotein convertase subtilisin/kexin type 9 (PCSK9), apolipoprotein C-III (apoC3) and small dense low density lipoprotein cholesterol (sdLDL-C), have been recently recognized as circulating atherosclerosis-related lipid measurements." (PMID 27713142, 2017). "Collectively, our observations highlight the possibility that targeting APOC3 may be beneficial for treating atherosclerosis and kidney disease in people with diabetes." (PMID 38743496, 2024). "Rather than increasing systemic inflammation, APOC3-containing lipoproteins or free APOC3 might have a number of local effects in lesions of atherosclerosis." (PMID 37972731, 2024).
atherosclerosis (continued). "This suggests that targeting APOC3 might benefit both diabetes-accelerated atherosclerosis and kidney disease." (PMID 38743496, 2024). "There is still much to learn about the mechanisms of action of different forms and pools of APOC3 in atherosclerosis and CVD, and whether APOC3 inhibition would prevent CVD risk in patients on LDL-cholesterol lowering medications." (PMID 37972731, 2024). "Moreover, APOC3 deficiency was found to be more beneficial in maintaining the TC, TG, and LDL-C levels, inhibiting inflammatory responses, and preventing atherosclerosis when fed a high-fat diet." (PMID 38927431, 2024). "In plasma, virtually all APOC3 is bound to TRLs, RLPs and HDL (and some to LDL), but it is possible that lipoprotein-free APOC3 could be generated in tissues, such as in lesions of atherosclerosis." (PMID 37972731, 2024). "The increased particle sizes and detrimental subspecies such as HDL containing apoC3 in individuals with high levels of HDL-C have been found to result in cholesterol deposition and atherosclerosis development, thereby increasing the risk of cardiovascular events." (PMID 39696353, 2024). "PCSK9 and APOC3 inhibitors have been successfully tested as treatments for atherosclerosis." (PMID 35677050, 2022). "Further studies should explore whether APOC3 contributes to ISR through multiple vascular mechanisms involving atherosclerosis and proinflammatory responses." (PMID 35265678, 2022). "Later studies confirmed that APOC3 overexpression promotes restenosis and atherosclerosis." (PMID 32849290, 2020). "ApoC3 overexpression in humans functions in atherosclerosis." (PMID 31936903, 2020). "Thus, elevated APOC3 appears to explain the effect of diabetes on TGs and atherosclerosis in this model." (PMID 32849290, 2020). "The accelerated atherosclerosis in diabetic mice was prevented by APOC3 silencing." (PMID 32849290, 2020). "In contrast, a recent study showed that non-mutated apoC3 gene carriers exhibited a favorable lipid profile, and revealed strong genetic evidence implicating the S2 allele in the development of atherosclerosis." (PMID 29162127, 2017). "In the present study, we, for the first time, addressed the association of 3 novel circulating atherosclerosis-related lipid measurements including PCSK9, apoC3 and sdLDL-C with current dyslipidemias, to investigate the roles of these markers in determining potential lipid disorders." (PMID 27713142, 2017). "This contrasts with the traditional view of HDL as protective against atherosclerosis, as APOC3-containing HDL has been associated with a negative impact on cardiovascular health, with studies indicating an 18% increased relative risk of CHD in individuals with elevated APOC3 levels." (PMID 39684468, 2024). "Therefore, it can be boldly speculated that APOC3 is closely related to the formation and development of atherosclerosis, in which a series of inflammatory responses play an important role." (PMID 34922545, 2021). "Since the SNPs at 11q23.3 region harbouring apolipoprotein coding genes namely APOA1, APOC3, APOA4, APOA5 and regulatory genes BUD13, ZPR1, SIK3 were found to be associated with defective lipid metabolism, this region was thought to play an important role in atherosclerosis and CAD risk." (PMID 33298998, 2020). "Accordingly, plasma APOC3 levels are elevated, clearance of TRLs/remnants is slowed, and plasma TRL remnants are increased in two mouse models of diabetes-accelerated atherosclerosis." (PMID 40709279, 2025).
atherosclerosis (continued). "An important role in the pathogenesis of atherosclerosis is played by the genes ALB, SHBG, APOC, APOC3, APOC4, and SAA4, of which APOC3 and APOC4 make a major contribution to the occurrence of atherosclerosis and also to insulin resistance and type 2 diabetes." (PMID 40361926, 2025). "Advancements in gene editing techniques, particularly zinc finger nuclease, helped to create more advanced genetic models, which include also models of atherosclerosis, such as APOE, APOC3 and CETP knockout (KO) rabbits." (PMID 39364866, 2025). "Apolipoprotein C3 (APOC3) is a key regulator of plasma triglycerides, and it has recently been suggested to play a role in both type 1 diabetes–accelerated atherosclerosis and kidney disease progression." (PMID 38743496, 2024). "Apolipoprotein C3 (ApoC3), a surface protein component abundantly found on circulating triglyceride-rich ApoB lipoproteins and HDL, is a major contributor to atherosclerosis, according to increasing evidence." (PMID 35453604, 2022). "Thus, high levels of APOC3 in HAs may be involved in the occurrence of atherosclerosis induced SLE." (PMID 35514958, 2022). "There was a striking protective effect of APOC3 inhibition by ASO on both early and more advanced atherosclerosis in this mouse model of type 1 diabetes-accelerated atherosclerosis." (PMID 32849290, 2020). "In the current study, we targeted hepatic Apoc3 expression with liver-specific ASOs and analyzed its effect on atherosclerosis development and progression dependent or independent of its triglyceride-lowering properties using mouse models." (PMID 35653195, 2022). "In another report that evaluated the association of ApoC3 with subclinical atherosclerosis in 58 patients with SLE, no atherogenic effect of ApoC3 was found." (PMID 35615358, 2022). "Besides this last one and PCSK9 inhibitors, also IONIS-ANGPTL3-LRX (target: hepatic ANGPTL3 mRNA; NCT02709850) and AKCEA-APOCIII-LRX (target: hepatic APOC3 mRNA; NCT02709850) are in development in the atherosclerosis field." (PMID 36505351, 2022). "Likewise, animal models convincingly show that increased clearance of TRLs and RLPs by LPL activation (achieved by inhibition of APOC3, ANGPTL3, or ANGPTL4 action, or increased APOA5) results in protection from atherosclerosis." (PMID 32849290, 2020). "It is possible that this difference could be explained by differences in dosing, off-target effects by the non-liver-targeted APOC3 ASO, or by APOC3 produced by the intestine, contributing to atherosclerosis." (PMID 40709279, 2025). "Our recent findings suggest that diabetes increases the ensnaring of pro-atherogenic particles containing APOB, APOC3, and APOE (indicating that they might be TRLs or RLPs derived from TRLs) in the artery wall and that this contributes to accelerated atherosclerosis." (PMID 32118048, 2020). "Thus, APOC3’s mechanism of action does not appear to be explained solely by its effects on plasma triglycerides, and the mechanisms whereby APOC3 promotes atherosclerosis may go beyond its effects on circulating triglycerides and cholesterol." (PMID 37972731, 2024).
dyslipidemia (105 papers, 2007 to 2026). "APOC3 (rs5128) was linked to higher BMI and an increased risk of dyslipidemia and obesity, with an OR of 4.022 (95% CI, 1.13–14.30) in a Kuwaiti Arab population study." (PMID 39684468, 2024). "Elevated APOC3 levels can worsen insulin resistance, triggering a cycle that elevates triglyceride levels and raises the risk of metabolic syndrome and diabetes." (PMID 39286687, 2024). "Variant APOC3 rs147210663 has been reported to be associated with dyslipidemia, cholesterol, and BMI over 40 times." (PMID 37372394, 2023). "In the APOC3 rs2854116 dominant model, patients with CT/CC genotype had a higher risk of dyslipidemia than those with TT genotype." (PMID 36759651, 2023). "In this sense, ApoC3 has been described to induce inflammation and organ damage by alternative inflammasome activation, and ApoC3 serum levels were associated with individual metabolic syndrome risk factors such as diabetes and inflammatory markers." (PMID 35584319, 2022). "Because loss-of-function mutations in ApoC3 are characterized by a strong decrease in serum triglycerides and decreased cardiovascular risk, ApoC3 has been suggested to be a potent therapeutic approach to control dyslipidemia and cardiovascular disease." (PMID 35637531, 2022). "More studies on diverse populations would be needed to clarify the putative role of rare variants in APOC3 or nearby genes (within the cluster) for their effects on dyslipidemia and CAD." (PMID 34548093, 2021). "An important role of polymorphisms tagging APOC3 is further convinced in the occurrence of dyslipidemia by Genome-Wide Association Studies (GWAS)." (PMID 33294458, 2020). "Recently, the APOC3 polymorphisms have been investigated the association with many diseases, such as metabolic syndrome 42, type 2 diabetes 43, coronary heart disease 44 and plasma APOC3 and lipid levels." (PMID 34394242, 2020). "Heritability studies revealed a strong genetic component to dyslipidemia, ranging from 0.20 to 0.60 in which these estimates are likely reflecting contributions from numerous gene variants including APOC3." (PMID 31856839, 2019). "High circulating concentration of APOC3 was shown to be associated with increased levels of triglycerides (TG) in blood and in metabolic disorders including dyslipidemia." (PMID 31856839, 2019). "It has been shown that the relationship of APOC3 genetic variants with metabolic syndrome risk is modified by diet." (PMID 30380775, 2018). "The aim of this study was to examine the interaction of dietary food groups and genetic variants of APOA1/APOC3, relative to Metabolic Syndrome (MetS) risk in adults." (PMID 28496949, 2017). "Plasma levels of PCSK9, apoC3, and sdLDL-C were associated with the current dyslipidemias classification (all p<0.001)." (PMID 27713142, 2017). "A nested case–control study demonstrated a diet-gene interaction between APOC3 rs5128 polymorphism and the western dietary patterns in relation to metabolic syndrome risk." (PMID 25994187, 2015). "Two other case–control study also suggested that two genetic variants (−482 C/T and −455 T/C) of APOC3 were associated with the metabolic syndrome." (PMID 25994187, 2015). "A case–control study suggested that APOC3 promoter polymorphisms (-482 C/T and -455 T/C) were associated with the metabolic syndrome." (PMID 25380998, 2014). "Variant alleles of APOC3 contribute to the development of dyslipidemia in AIDS patients even prior to HAART initiation." (PMID 24972136, 2014). "In summary, there was evidence for a differential risk of HAART-associated dyslipidemia conditioned by the APOC3 haplotype pair." (PMID 22848358, 2012). "In order to assess the effect of APOC3 alleles on lipid levels and risk of dyslipidemia, and to check potential confounders or interactions, the contribution of treatment- and time-dependent factors were collectively evaluated." (PMID 22848358, 2012).
dyslipidemia (continued). "The gene region of Apolipoprotein C-III (APOC3) contains three of the most studied polymorphisms associated with HAART-related dyslipidemia." (PMID 22848358, 2012). "Variants of APOC3 m455 and m482 have been associated with altered glucose metabolism and metabolic syndrome." (PMID 19424489, 2009). "The other haplotype (CCTTC, carrying the APOA5 12,238C, the APOA4 Ser347 and the APOC3 -482T alleles) was associated with a 26% reduction in metabolic syndrome risk (p = 0.03)." (PMID 18789138, 2008). "Another genetic origin that could lead to the development of NAFLD is single-nucleotide polymorphisms (SNPs) of apolipoprotein C3 (APOC3), which plays an important role in lipid metabolism and dyslipidemia." (PMID 39125855, 2024). "Additionally, elevated levels of APOH, APOC2, and APOC3 have been linked to clinically apparent arteriosclerosis and components of metabolic syndrome (MetS)." (PMID 38034020, 2023). "APOC3 has been repeatedly associated with dyslipidemia and blood lipids." (PMID 37372394, 2023). "The common genetic variant of APOC3 contributes to metabolic syndrome in adults." (PMID 26485402, 2015). "The rs2854116 in the APOC3 carries a significantly increased risk of CC/CT genotype compared with those carrying TT genotype, suggesting that the C allele of rs2854116 locus may be associated with the development of dyslipidemia." (PMID 36759651, 2023). "However, ApoC3 deficiency protects against dyslipidemia and atherogenesis." (PMID 35453604, 2022). "The recent 2026 American College of Cardiology/American Heart Association dyslipidemia guideline emphasizes the clinical importance of targeting PCSK9, APOC3, Lp(a), and ANGPTL3." (PMID 42164756, 2026). "When APOC3 levels are high, the likelihood of developing metabolic syndrome and type 2 diabetes increases." (PMID 39286687, 2024). "In humans and mice with human-like dyslipidemia, APOC3 is distributed across most lipoprotein classes, including VLDL, LDL, and HDL particles." (PMID 38743496, 2024). "This study uses OS and genes (LYPLAL1, APOC3 and SOD2) as research variables, and explores their association with dyslipidemia in coal workers from the perspective of the interaction between environment and genetics." (PMID 36759651, 2023). "In males and females with dyslipidemia, a significant inverse correlation was observed between E2 and ApoC3." (PMID 36855114, 2023). "It is fruitful to look into the relationship between ApoC3 and E2 among participants with dyslipidemia because estrogen and blood lipid metabolism are closely related." (PMID 36855114, 2023). "Our in vivo study indicated that dyslipidemia not only elevated the level of ApoC3 in the apolipoprotein component of LDL, but that it also induced vascular endothelial senescence and enlarged the atherosclerotic lesion size." (PMID 35453604, 2022). "Single-nucleotide polymorphisms (SNPs) of apolipoprotein C3 (APOC3) play important role in lipid metabolism, and dyslipidemia underlies nonalcoholic fatty liver disease (NAFLD)." (PMID 33294458, 2020). "The critical role of APOC3 in lipid metabolism, together with the dyslipidemia caused by APOC3 mutations and apolipoprotein C3 deficiency, suggests an association of APOC3 SNPs and dyslipidemia-based NAFLD." (PMID 33294458, 2020). "The important role of APOC3 in lipid transport and metabolism deems it necessary to reveal the full genetic profile of single nucleotide polymorphisms (SNPs) at this locus and how they may correlate to inter-ethnic susceptibility of dyslipidemia and other metabolic abnormalities." (PMID 31856839, 2019). "Many genetic variants involved in the pathogenesis of the metabolic syndrome had been found to be associated with lipid metabolism, namely, SNPs in the APOA5, APOC3, and CETP genes." (PMID 29666642, 2018). "PCSK9, apoC3, and sdLDL-C showed significant interactions with current dyslipidemias, and were predictive in the screening." (PMID 27713142, 2017).